ERBB2 (erb-b2 receptor tyrosine kinase 2)
Diseases named in the same sentence as ERBB2 in open-access papers (continued):
Sharing a sentence is not in itself a finding about the gene and the disease.
breast cancer (continued). "Certain CNVs, such as the amplification of ERBB2 gene, occur at a high frequency in specific breast cancer phenotypes, such as HER2-positive breast cancer (20–40% of the cases)." (PMID 34281208, 2021). "Of note, the cytotoxicity of NK-92/5.28.z cells against aRMS cells was similar to that of NK-92/5.28.z cells against MDA-MB-453 breast cancer cells, which highly overexpress ERBB2." (PMID 33809981, 2021). "The current studies also reveal that ErbB2-overexpressing breast cancer cells with low CHIP expression exhibit higher induction of endoplasmic reticulum stress." (PMID 34439093, 2021). "This signature measured the impact and actionability of the ERBB2 alterations, and exhibited potential clinical value by being predictive of neratinib response in breast cancer cell line data." (PMID 33413533, 2021). "In this work we evaluated the capacity of Rlip knockout to prevent breast cancer in genetically engineered mouse models of HER2-driven breast cancer (Erbb2 model) and polyomavirus-driven breast cancer (PyVT model)." (PMID 34283045, 2021). "In line with this, downstream of TGFβ and ErbB2 signaling pathways, CdGAP was shown to regulate cell migration and invasion in an ErbB2-induced mouse breast cancer cell model." (PMID 34493786, 2021). "Studies from our group and others indicate that the pro-metastatic role of CD151 in human basal-like and ErbB2 breast cancer subtypes is achieved largely through regulating α6 integrin-dependent cell motility, invasion and survival." (PMID 33919420, 2021). "Reduced CHIP expression was seen in breast cancer patient tumors and in ErbB2-overexpressing and Triple Negative Breast Cancer (TNBC) cell lines." (PMID 34439093, 2021). "The decrease in S6K1 and AKT phosphorylation upon DEPTOR silencing suggested that the reduction in the levels of ErbB2 by DEPTOR knockdown appears to play a major role in suppressing the PI3K/AKT/mTOR pathway in ErbB2-positive breast cancer cells." (PMID 33995662, 2021). "The clinical use of ERBB2-targeted drugs, such as trastuzumab, pertuzumab and lapatinib, improved outcomes for breast cancer and colorectal cancer patients with ERBB2 amplification." (PMID 34663410, 2021). "To establish that the ErbB2-overexpressing breast cancer cell lines SKBR3 and 21MT1 have an inducible ER stress pathway, we treated these cells with thapsigargin, a commonly used ER stress inducer." (PMID 34439093, 2021). "One of the key amplified oncogenes found in particularly breast, stomach, esophageal, and uterine cancers is ERBB2 (also called HER2/Neu), which we found here to cause AU-rich mRNA stabilization in breast cancer cells." (PMID 34535639, 2021). "About 15–20% of primary breast cancer patients have HER2/erbB2 oncogene overexpression or exhibit amplification, which is associated with aggressive tumor behavior and a poor clinical outcome." (PMID 34771622, 2021). "We stratified 59 breast cancer cell lines based on ERBB3 or ERBB2 expression by mining the publicly available Cancer Cell Line Encyclopedia (CCLE) database." (PMID 33420373, 2021). "We used SNAPD to evaluate the expression of the HER2 (ERBB2) breast cancer marker in two cell lines." (PMID 34233007, 2021). "The IHC staining with anti-PCNA, anti-ErbB2, and anti-caspase-3 detected PCNA, ErbB2, and caspase-3-positive cells, respectively, in the rat mammary tumors." (PMID 34164110, 2021). "The presented data demonstrate efficient ErbB3 targeting by the single-domain antibody in breast cancer cell cultures, and visualize the existence of isolated clusters of “oncogenic units”, where signaling through ErbB2/ErbB3 heterodimers does occur." (PMID 34572289, 2021).
breast cancer (continued). "It has been reported that Akt3 can contribute to the proliferation of ErbB2 (HER2)-positive breast cancers which express low levels of ERα and contribute to endocrine resistance." (PMID 34298660, 2021). "Other studies suggest that binding of CPNE3 to ERBB2 is increased when Jab1 is overexpression in SKBR3 breast cancer cells." (PMID 35003348, 2021). "Lapatinib, a synthetic quinazoline derivative, is an orally active reversible ErbB1 and ErbB2 tyrosine kinase receptor inhibitor that possesses antineoplastic activity towards breast cancer." (PMID 34946704, 2021). "The breast cancers arising in the ErbB2 transgenics strongly resembled the breast cancers arising from the mammary fat pad-injected ErbB2-iPSC clones." (PMID 34044885, 2021). "Among patients with breast cancer with available immunohistochemical tumor markers (ER, PR, and ERBB2), 59.6% (344 of 577) of breast cancers were ER positive and 24.1% (129 of 536) were triple negative (TNBC)." (PMID 33646313, 2021). "We determined an ERBB2 estimated CN threshold of 3.2 for recommending anti-HER2 therapy in breast cancer cases." (PMID 33710417, 2021). "In recent years, targeted therapy of ErbB2 has become a research hotspot in breast cancer treatment, and the upregulation of ErbB2 receptor was closely related to the occurrence of breast cancer." (PMID 33995007, 2021). "As expected, RIP, RNA pull-down and dual-luciferase reporter assays confirmed the binding of circ-ERBB2 to miR-136-5p or miR-198 in HER2-positive breast cancer cells." (PMID 34732216, 2021). "SK-BR-3, established in 1970 from the pleural effusion of a Caucasian female with malignant breast adenocarcinoma, is a human breast cancer cell line overexpressing ERBB2 gene product." (PMID 34681026, 2021). "Recently, we generated a p140Cap interactome from the ERBB2-positive breast cancer TuBo cell, a clonal line established in vitro from a BALB-NeuT mouse mammary carcinoma." (PMID 34708040, 2021). "We evaluated STRAT4/IHC ESR1/estrogen receptor (ER), ERBB2/human epidermal growth factor receptor 2 (HER2) concordance rates of 150 breast cancer tissues processed in Rwanda, with undocumented cold ischemic and fixation time." (PMID 34050358, 2021). "In accordance, mice with disrupted expression of NBCn1 show delayed tumor development and decelerated tumor growth when tested using models of carcinogen- and ErbB2-induced breast cancer." (PMID 34219652, 2021). "Tumor suppression functions of Tid1 rely on degradation of ErbB2 in breast cancer, and attenuation of EGFR/Akt/Erk signaling in HNSCC and in NSCLC." (PMID 33406664, 2021). "ErbB2+ tumors are presented in 11–30% of total breast cancer cases; their treatment involves the use of ErbB2-targeted therapeutics." (PMID 34944558, 2021). "In ErbB2+ BC cells, ECD regulates ErbB2 mRNA export and stability and is required for ErbB2+ breast cancer cell proliferation, anchorage-independent growth, migration, and invasion." (PMID 33941617, 2021). "For example, MTCH2 was down-regulated in ErbB2-driven mammary carcinoma, and its induction reduced tumorigenicity and leads to growth arrest of breast cancer." (PMID 33509092, 2021). "Using ErbB2-overexpressing breast cancer cell lines, we implicate ECD as a regulator of ErbB2 mRNA export and stability to promote ErbB2-driven oncogenic traits." (PMID 33941617, 2021). "For example, deletion of the ITGB4 signaling domain in a mouse model of ErbB2-induced mammary carcinoma resulted in suppression of tumor growth and metastasis, and improved efficacy of ErbB2-targeted therapy." (PMID 34504657, 2021). "STARD10 was found to be coexpressed with ERBB2 in certain breast carcinoma cell lines, suggesting an increase in cell proliferation for tumors expressing both proteins." (PMID 34572920, 2021).
breast cancer (continued). "HER2-positive breast cancer (HER2+-BC) is characterized by the overexpression and/or amplification of the ERBB2 gene encoding the epidermal growth factor receptor 2, which occurs in ≈15–20% of all breast cancers (BC)." (PMID 34007022, 2021). "ErbB2-iPSC clones also gave rise to mammary carcinomas which exhibited dual GFP autofluorescence and ErbB2 membrane red immunofluorescence." (PMID 34044885, 2021). "Meanwhile, upregulation of GRB2 (log FC = 3.9, p = 0.016) and ERBB2 (log FC = 5.6, p = 0.026) expression was detected in mammary carcinoma tissue with grade III (n = 3)." (PMID 34679042, 2021). "The presence of human epidermal growth factor receptor 2 (HER2), also known as ERBB2, amplification confers an aggressive breast cancer phenotype." (PMID 34349115, 2021). "In the same family of EGFR is human epidermal growth factor receptor-2 (HER2 or ErbB2), a well-known proto-oncogene in mammary carcinomas." (PMID 34660770, 2021). "As biomarkers, PR, ER, and ERBB2/HER2 can be used as prognostic targets of breast carcinoma and are helpful to suggest the most appropriate chemotherapeutic treatments." (PMID 33757543, 2021). "Our study shows that 57% of ++Oxtr females develop ERBB2+ mammary tumors with change of PI3K-AKT, MAPK, Jak-STAT, and NF-kappa B pathways, similar to HER2+ breast cancer." (PMID 34099636, 2021). "At present, T-DM1 is under investigation in 36 active phase I–III clinical trials registered on ClinicalTrials.gov in ErbB2-positive breast cancer, lung cancer, colorectal cancer and other solid tumors in various combinations." (PMID 33081383, 2020). "MEDICA efficacy and mode of action in the ErbB2 context was studied in ErbB2 transgenic mice and human breast cancer cells." (PMID 32695336, 2020). "In contrast to mTOR canonical inhibitors, treatment of ErbB2 breast cancer by MEDICA allows for both, inhibition of mTORC1 activity while concomitantly disrupting ErbB family members and their signaling cascades." (PMID 32695336, 2020). "Depletion of AKT3 induced ERα re-expression and increased the effectiveness of tamoxifen in ErbB2+/ ERα- breast cancer cells." (PMID 32042339, 2020). "It hence implies that the USP2 inhibitor ML364 is capable of potentiating a wide range of HSP90 inhibitors to suppress ErbB2 levels in breast cancer cells." (PMID 32327714, 2020). "Previously, we and others reported that paired box 2 protein (PAX2) is a key factor in breast cancer by repressing the transcription of ERBB2/HER2 in ER-positive (ER+) breast cancer." (PMID 32843722, 2020). "We choose trastuzumab-based treatment for ERBB2 + breast cancer as an example of an oncogenic kinase-driven tumor where proteogenomic analyses and pharmacodynamic studies should provide significant insights into variability in treatment outcomes." (PMID 31988290, 2020). "In this cohort study of 239 211 women with breast cancer, the incidence of HR-negative and ERBB2 (formerly HER2)–positive, HR-positive and ERBB2-positive, and triple-negative breast cancer was higher in Black women compared with non-Hispanic White women." (PMID 33074325, 2020). "It showed that MZF1, upon activation by ErbB2 signaling, can induce the pericellular accumulation of lysosomes at the invadosome-like cellular protrusions in invasive ErbB2 expressing breast cancer cells, thereby initiating and promoting their invasion." (PMID 31963147, 2020). "In particular, ErbB2 overexpression categorizes a subclass of breast cancer called ErbB2/Her2-positive, which represents approximately 20–30% among all type breast malignancies and is generally associated with poor prognosis." (PMID 32327714, 2020).
breast cancer (continued). "While AKT1 is pro-tumorigenic in lung cancer and ErbB2 positive breast cancer, its silencing is pro-tumorigenic in prostate and other types of breast cancer." (PMID 32764385, 2020). "In trastuzumab-resistant ErbB2-positive breast cancer cells, the improved glycolytic rate is regulated by heat shock factor 1 and LDHA and inhibition of glycolysis with 2-DG and the LDH inhibitor oxamate by-pass trastuzumab resistance." (PMID 32211323, 2020). "In breast cancer, 14-3-3ζ cooperates with ErbB2 to promote the progression of ductal carcinoma in situ to invasive breast cancer by inducing EMT." (PMID 33123465, 2020). "ErbB2 (HER2) breast tumors comprise 20–25% of breast cancer cases, half of which are also hormone-receptor positive (Luminal B)." (PMID 32695336, 2020). "Of particular interest, one SMNT was involved in transforming focal amplification of the ERBB2 gene in a HER2+ breast cancer genome." (PMID 32024997, 2020). "Well-known examples are breast cancers with amplified receptor tyrosine-protein kinase erbB-2 (HER2/neu)." (PMID 33182817, 2020). "The appearance of the peripheral population of lysosomes correlates positively with the invasiveness of ErbB2 positive ovarian and breast cancer cells and can contribute to extracellular matrix (ECM) degradation both internally and externally." (PMID 31963147, 2020). "Cell- or tissue-specific EV markers have also been reported, such as TSPAN8 and EPCAM (epithelial cell), CD37 and CD53 (leukocytes), PECAM1 (endothelial cells), and ERBB2 (breast cancer)." (PMID 32847103, 2020). "To assess the involvements of lysosome function in 17-AAG-incurred ErbB2 degradation, we treated ErbB2-positive breast cancer cells with chloroquine that blocked the acidification of lysosomes." (PMID 32327714, 2020). "We performed a model-based economic evaluation that examined the cost-effectiveness of 5 neoadjuvant followed by adjuvant treatment strategies for ERBB2-positive breast cancer by modeling our patient population and outcomes based on the KATHERINE trial." (PMID 33226431, 2020). "Following the discovery of erythroblastic oncogene B2 (ERBB2) gene amplification in breast cancer, the human epidermal growth factor receptor 2 (HER2) has emerged as an attractive target for antibody therapies." (PMID 32079309, 2020). "We have recently reported the influence of cell membrane fluidity and rigidity on the surface accumulation of ErbB2, which can be exploited to design therapeutic strategies against ErbB2-positive breast cancer." (PMID 32327714, 2020). "For example, epidermal growth factor 2 (ERBB2/HER2) is a transmembrane receptor tyrosine kinase that is overexpressed in approximately 20% of all breast cancer patients." (PMID 32906686, 2020). "We show that ERRFI1 is selectively downregulated in ERα-positive breast cancers and breast cancers driven by ERBB2." (PMID 33046784, 2020). "ErbB2-targeting therapy using therapeutic antibodies has been successful in breast cancer treatment." (PMID 32599712, 2020). "In this economic evaluation, a decision-analytic model was developed to evaluate various neoadjuvant followed by adjuvant treatment strategies for women with ERBB2-positive breast cancer from a health care payer perspective in the United States." (PMID 33226431, 2020). "Results from colony formation and cell cycle analyses revealed that ML364 significantly enhanced the inhibitory effects of 17-AAG to hinder the cell cycle progression and curb the growth of breast cancer cells with ErbB2 overexpression." (PMID 32327714, 2020). "MCF7/HER2 and BT-474 breast cancer cell lines overexpressed the oncogenic receptor tyrosine kinase, HER2/ErbB2, which activates NF-κB and diminishes the responsiveness to tamoxifen." (PMID 32823992, 2020). "We have developed a highly specific cancer-targeting drug delivery system using a targeting peptide to maximize the therapeutic efficiency of rapamycin and to help prevent drug resistance in ErbB2-positive breast cancer." (PMID 32599712, 2020).
breast cancer (continued). "MEDICA treatment is shown here to suppress ErbB2 breast cancer in vivo and cell lines by targeting mitochondrial oxidative phosphorylation, resulting in suppression of ErbB family members and inhibition of mTORC1 activity." (PMID 32695336, 2020). "This time period includes the most complete data on breast cancer molecular subtypes, including ERBB2 status, to our knowledge." (PMID 32804214, 2020). "CTC‐ITB‐01 cells showed a luminal B breast cancer subtype (ER+, ERBB2−); in particular the stable ER expression is remarkable in view of the paucity of ER+ breast cancer cell lines." (PMID 32667137, 2020). "This association of high levels of ECT2-Ex5 inclusion with bad prognosis specifically in case of chemotherapeutic treatment, was even more pronounced in the HR+ERBB2– subtype of breast cancer." (PMID 31943118, 2020). "It is suggested that AFAP1‐AS1 enhances the translation of ERBB2 by associating with AUF1, whereas SNHG14 regulates the BCL‐2/BAX signalling pathway in breast cancer cells." (PMID 32924276, 2020). "Frequently affected genes by CNVs in Chinese breast cancer patients were ERBB2 (25%), MIEN1 (25%), GRB7 (24%), TRPS1 (6%), MYC (6%), ERLIN2 (6%), PLPP5 (6%), NSD3 (6%), FGFR1 (6%), and CCND1 (5%)." (PMID 33173047, 2020). "T-DM1 was compared with the treatment of physician’s choice in another phase III TH3RESA study in ErbB2-positive advanced breast cancer patients previously treated with two or more ErbB2-directed regimens, including trastuzumab." (PMID 33081383, 2020). "Our study demonstrates that the heterogeneity in response to T-DM1 is partly explained by ERBB2 levels and provides a clinically applicable assay to be tested in future clinical trials of breast cancer and other cancer types." (PMID 32674482, 2020). "This economic evaluation modeled the cost-effectiveness of 5 neoadjuvant-adjuvant treatment strategies for women with ERBB2-positive breast cancer." (PMID 33226431, 2020). "EphA2 has been reported to be associated with cancer stem-cell qualities, and to promote tumor neo-angiogenesis, and metastasis, including cross-talk with erbB receptor signaling to control initiation and spread of erbB2-dependent mammary tumors in mice." (PMID 32397088, 2020). "Subsequently, HSF1-null mice were also shown to be resistant to carcinogen-induced liver cancer and HER2/ErbB2-induced breast cancer." (PMID 32408596, 2020). "This cohort included patients in which NGS testing revealed positivity for targets such as HER2/neu (ERBB2) in breast cancer specimens, androgen receptor (AR) in prostate cancer, BRAF in melanoma and EGFR mutation in NSCLC." (PMID 32760731, 2020). "Next we sought to evaluate the combination of USP2 and HSP90 inhibitors using ErbB2-positive breast cancer xenograft mouse models." (PMID 32327714, 2020). "Since the observation of geldanamycin-incurred ErbB2 degradation, different intracellular itineraries and degradation pathways for ubiquitylated ErbB2 have been proposed in ErbB2-positive breast cancer cells exposed to HSP90 inhibitors." (PMID 32327714, 2020). "As a demonstration, we analyze core needle biopsies from ERBB2 positive breast cancers before and 48–72 h after initiating neoadjuvant trastuzumab-based chemotherapy." (PMID 31988290, 2020). "The development of trastuzumab, which is an ErbB2-specific antibody also known as Herceptin, has had a great effect on breast cancer treatment." (PMID 32599712, 2020). "Retrospective clinical studies have indicated improved disease-free and overall survival of diabetic ErbB2 luminal B breast cancer patients treated with metformin." (PMID 32695336, 2020).